PER2 (period circadian regulator 2)
Diseases named in the same sentence as PER2 in open-access papers (continued):
Sharing a sentence is not in itself a finding about the gene and the disease.
depression (continued). "In addition, scientists have found that melatonin receptor agonists relieved patients’ depression and anxiety with decreased Per1, Per2, Cry1, Cry2 and Nr1d1 expression." (PMID 36699021, 2022). "In rodent models of depression, dysregulation of circadian gene expression has been observed, with Bmal1 and Per2 as the more affected; normal rhythms could be reinstated after imipramine or melatonin treatment." (PMID 36430520, 2022). "Variations in the Per2 genes are connected to depression vulnerability in humans." (PMID 33509094, 2021). "This suggests that Per2 in glial cells may play an important role in the development of despair-based behavior contributing to depression." (PMID 34112905, 2021). "Intriguingly, Bhlhe40, Dbp and Nr1d2 are among the top-ranked genes that are rhythmically expressed in the human brain, and individuals with major depressive disorder appear to have lost the alignment between Bhlhe40 and Per2 expression timetables in six brain regions, e.g. in the amygdala." (PMID 25820768, 2015). "Therefore, a deficiency in Per2 results in increased levels of dopamine, which may account for reduced depression-like behaviors in Per2-KO mice." (PMID 37606043, 2023). "We speculate that these similarities, especially the alterations in the brain’s reward systems related to dysfunction of neurotransmitter systems, might partly explain why the Per2 mutant mice exhibited an alteration in ultradian locomotor dynamics, as also observed in human depression." (PMID 23516567, 2013). "The rs934945 SNP might influence the interaction between PER2 and other clock genes (e.g., CLOCK, BMAL1), leading to dysregulation of the circadian network and increased susceptibility to sleep disorders when combined with psychological stressors like anxiety and depression." (PMID 40951374, 2025). "Knockdown of either CREB or Per2 in CA1 produces mania-like behaviors, while overexpression of either in this region leads to depression-like behaviors." (PMID 40011706, 2025). "shRNA knockdown of CREB or Per2 in CA1 region induced mania-like behavior, while overexpression of both factors resulted in depression-like behavior." (PMID 40011706, 2025). "Per2 silencing in mPFC produced antidepressant-like effects, while REV-ERB agonism enhanced the depression-like phenotype and suppressed ketamine action." (PMID 39179578, 2024). "Another melatonin receptor agonist, ramelteon, improves depression and anxiety symptoms by increasing BDNF levels and targeting clock genes (e.g., Per1 and Per2)." (PMID 36699021, 2022). "Therefore, knockdown of Per2 in the CA1 leads to mania-like behavior—evidenced by increased sucrose preference and locomotor activity, along with decreased impulsivity- and depression-like behavior." (PMID 40011706, 2025). "In contrast, knockout (KO) of Per2 in either neurons or glia of the NAc reduced depression-like behavior without affecting impulsivity-like behavior." (PMID 40011706, 2025). "In the present study, we tested the hypothesis that deletion of the Per2 gene, an essential regulator of the circadian clock disrupts the HPA axis and related behaviors, such as depression-like and startle/sensorimotor gating behaviors in mice." (PMID 33509094, 2021). "Mice lacking both Per1 and Per2 showed robust increase in anxiety and depression phenotypes." (PMID 37441675, 2023). "Therefore, we assumed that glial Per2 plays a subordinate or no role in the anhedonia aspect of depression." (PMID 34112905, 2021). "All three approaches, the genetic as well as the AAV approaches revealed that absence of Per2 in glial cells, in particular the NAc, reduced the immobility time of mice in the FST, a test that assesses despair-based behavior, one of the aspects of depression." (PMID 34112905, 2021).
colorectal cancer (27 papers, 2011 to 2025). A primary or metastatic malignant neoplasm that affects the colon or rectum. "By applying MC38, a colorectal cancer cell line, in a syngeneic mouse model of liver metastasis, Per1–/–Per2–/– mice had reduced liver metastasis, and Per2–/– livers had less cancer-associated fibroblasts infiltration and collagen deposition." (PMID 33816508, 2021). "Moreover, the expression of per2 was negatively associated with the expression of miR-34a in tumours of patients undergoing surgery for colorectal cancer treatment at a more advanced stage of disease." (PMID 38398026, 2024). "In addition, high expression of PER2 gene was associated with significantly better outcomes in liver metastasis of colorectal carcinoma, and high PER2 protein levels are protective from carbon tetrachloride-induced hepatotoxicity." (PMID 23593233, 2013). "Conversely, PER2 knockdown in colorectal cancer cells activated the Snail/Slug-related EMT pathway, promoting proliferation and invasiveness of cancer cells." (PMID 38813085, 2024). "Our group has previously demonstrated that the expression of miR-34a effectively inhibits the expression of per2 in the colorectal cancer cell lines DLD1 and LoVo." (PMID 38398026, 2024). "Recent studies identified significant changes in PER2 expression in tumors such as chronic lymphocytic leukemia, kidney cancer, head and neck squamous cell carcinoma, and colorectal cancer." (PMID 38074100, 2023). "Here, we used the human colorectal cancer (CRC) cell line HCT116 and its knockout variants for different core-clock genes (BMAL1, PER2, NR1D1), to investigate the treatment effect of C. cardunculus lipophilic leaf extract under different clock scenarios." (PMID 36012399, 2022). "PER2 is considered a prognostic predictor in several human cancer types, including lung cancer, colorectal cancer, and gastric cancer." (PMID 35116071, 2022). "Downregulated PER2 was associated with a higher likelihood of EMT in breast tissue, while downregulated BMAL1 decreased the invasion of mesenchymal cells in colorectal cancer." (PMID 35356228, 2022). "GADD45A acts as a tumour suppressor and was found to be correlated with the expression of the core-clock gene PER2, in human colorectal carcinoma tissues." (PMID 34885088, 2021). "An altered rhythm of PER2 mRNA with lower mesor and amplitude in tumour tissue compared to normal colonic tissue was reported in mice with experimentally-induced colorectal carcinoma." (PMID 31658284, 2019). "Another study found that mRNA expression levels of Cry2 and Per2 were down regulated in colorectal cancer." (PMID 23626715, 2013). "To elucidate a possible mechanism to explain the hPer2 expression patterns in colorectal cancer, we further analyzed hPer2 mRNA levels in these 24 paired tissues which showed low expression of Per2 protein in tumor." (PMID 22166120, 2011). "As HSP70 has previously been observed to enhance AKT stability by binding to AKT in colorectal cancer cells, we hypothesized that a PER2/HSP70/AKT complex would form in OSCC cells, with effects on AKT stability." (PMID 40113747, 2025). "Downregulation of PER2 expression is related to poor outcomes in several tumors, including chronic lymphocytic leukemia, renal cancer, head, and neck squamous cell carcinoma, colorectal cancer, and others." (PMID 38074100, 2023). "Apart from prostate cancer, defects in circadian rhythm may cause various other cancer types, such as colorectal cancer due to the PER2–ATM–Chk1/Chk2 pathway." (PMID 37475884, 2023).
colorectal cancer (continued). "Since it has been shown that CpG methylation can inactivate promoter function, leading to inhibition of hPer gene promoter function in breast and endometrial carcinoma, whether CpG methylation on the PER2 promoter contributes to human colorectal cancer development needs further investigation." (PMID 22166120, 2011). "In colorectal cancer, increased levels of BMAL1 have been related to decreased survival, and similarly, reduced levels of PER2 and PER3 have led to more inadequate tumor differentiation." (PMID 35356228, 2022). "Upregulation of PER2 and CRY1 in gastric cancer and CRY1 in colorectal cancer correlate with more advanced disease states and lymph node metastasis." (PMID 31014368, 2019). "In previous studies, we identified altered mRNA levels of the clock genes PER2 and CRY2 in colorectal carcinoma tissue compared to healthy tissue." (PMID 31658284, 2019). "For example, the core circadian pathway members PER2 and BMAL1 serve as tumor suppressor in lung cancer, BMAL1 and CLOCK respectively act as tumor suppressor and oncogene in colorectal cancer, BMAL1 inhibits ferroptosis to increase the oncogenesis of acute myeloid leukemia." (PMID 38951864, 2024). "Interestingly, the upregulation of miR-34a in colorectal cancer correlates with a decreased expression of Period1 (PER1) and Period 2 (PER2) genes, which are core components of the circadian clockwork mechanism." (PMID 33291485, 2020). "Currently there is no report on the direct regulation of PER2 by miR-32, but miR-32 can target phosphatase and tensin homologue (PTEN) and promote growth, migration, and invasion in colorectal carcinoma cells." (PMID 24171174, 2013).
lung carcinoma (24 papers, 2018 to 2025). "It has been reported that KMT2D loss directly decreases the expression of PER2 or IGFBP5 in lung cancer and melanoma respectively, which leads to the subsequent increased glycolysis." (PMID 39117659, 2024). "Loss of KMT2D in lung cancer disrupts enhancer signatures genome wide, including one regulating the circadian clock gene period circadian regulator 2 (PER2)." (PMID 34109280, 2021). "In another study, it was shown that loss of Per2 function accelerated lung cancer formation in mutant mice." (PMID 30375470, 2018). "In oral squamous cell carcinoma, low PER2 expression was connected to poor prognosis, tumor grade progression, and lymph node metastasis, whereas in lung cancer, increased PER2 expression was associated with less malignant differentiation and fewer lymph node metastases." (PMID 38813085, 2024). "It is frequently mutated in lung cancer, and its lung-specific loss in mice was demonstrated to promote lung cancer by impairing the super-enhancers, including the super-enhancer of the circadian rhythm repressor PER2, which regulates many glycolytic genes." (PMID 33302406, 2020). "Yet, disinhibition of these PER2-dependent glycolytic genes nevertheless sufficiently reprograms the SE landscape of these genes to sustain a metabolic dependency in this subset of lung cancer with increased sensitivity to glycolysis inhibiton." (PMID 37415185, 2023). "Loss of KMT2D reduces the activity of super-enhancers at critical genes, such as the circadian rhythm repressor Per2, resulting in Per2 gene down-regulation, glycolysis and lung cancer tumorigenesis." (PMID 38135679, 2023). "Inhibition of lung cancer metastasis and progression is elicited by Per2 and Bmal1." (PMID 39012661, 2024). "The log-rank test indicated a significant association of mRNA levels with overall survival (OS) of lung cancer patients (P < 0.05), and the TIMELESS, RORA, PER2, and CRY2 expressions were significantly correlated with progression-free survival (PFS) in lung cancer patients (P < 0.05)." (PMID 35078435, 2022). "Another study discovered that Per2 may influence glycolytic gene expression to affect lung cancer growth." (PMID 35599595, 2022). "Moreover, lower mRNA of PER1, PER2 and PER3 are linked to poor overall survival rates in lung cancer patients, indicating that these genes are prognostic markers." (PMID 34162762, 2021). "The same study clearly demonstrated that PER2 knockdown promoted proliferation and survival of resistant lung cancer cells by activating the PI3K/AKT/mTOR signaling pathway, whereas overexpression of PER2 protein inhibited this signaling pathway and induced apoptosis of resistant cells." (PMID 33114496, 2020). "Collectively, lung cancer patients with high expression of TIMELESS or low expression of RORA, PER1, PER2, or CRY2 had a significantly poorer prognosis in OS." (PMID 35078435, 2022). "Loss of histone methyltransferase KMT2D (also known as MLL4) in lung cancer results in a global reduction in SE acetylation levels due to inhibition of H3K4 methylation at promoters, including at the transcription factor PER2 which negatively regulates glycolytic genes." (PMID 37415185, 2023). "Furthermore, we used the CCLE to analyze mRNA expression levels of PER1, PER2, PER3, CRY1, and CRY2 in lung cancer cell lines in current lung cancer research." (PMID 36385012, 2022). "In lung cancer, lysine methyltransferase 2D (KMT2D) is highly expressed and regulates the super enhancers H3K4me1 and H3K27ac of period circadian regulator 2 (PER2; circadian inhibitory factor), affecting the expression of PER2 and its downstream glycolytic genes." (PMID 35004688, 2021). "MiR-92b-5p might promote lung cancer and non-small-cell lung cancer cell growth and controlled the G1/S cell cycle phase in human ES cells; furthermore, FADD and PER2 genes were reported to be related to reproductive deficits and embryogenesis." (PMID 31781648, 2019).
lung carcinoma (continued). "However, unlike in lung cancer where up-regulated KRAS disrupts the circadian gene PER2 leading to increased activation of glycolytic pathways, this disruption is not observed in our patient’s tumor." (PMID 40523964, 2025).
diabetes (20 papers, 2012 to 2025). "However, it is also necessary to say that the genetic component could be protecting our health such as in the case of polymorphisms associated with Per2 and Cry2 genes in diabetes, alcohol intake, and cancer." (PMID 27313610, 2016). "Diabetes alters the circadian rhythm of the corneal epithelium in mice, such that the expression of Clock, Bmal1, and Per2 is downregulated, and the expression of Cry1 and Rev-erbα is upregulated." (PMID 39062510, 2024). "Using RT-PCR, we examined two circadian genes Per2 and Bmal-1 in the colon to determine if diabetes affects the host circadian clock." (PMID 31569518, 2019). "Per2 mRNA expression was significantly elevated in the night in both control and diabetic mice, albeit with a trend to be more elevated in diabetes." (PMID 31569518, 2019). "Diabetes altered the circadian rhythm of the corneal epithelium in mice, such that the expression of Clock, Bmal1, and Per2 was downregulated, and the expression of Cry1 and Rev-erbα was upregulated." (PMID 27611469, 2016). "In this study, we show that diabetes influenced the circadian rhythm in the expression of five core clock genes (Clock, Bmal1, Per2, Cry1, and Rev-erbα), as well as mitosis, in the normal murine corneal epithelium." (PMID 27611469, 2016). "Diabetes downregulated Clock, Bmal1, and Per2 expression, upregulated Cry1 and Rev-erbα expression, reduced corneal epithelial mitosis, and increased leukocyte (neutrophils and γδ T-cells) recruitment to the cornea." (PMID 27611469, 2016). "Diabetes remission following VSG in GK rats is associated with increased expression of Dbp, Per1, Per2 and Per3 and decreased expression of Naps2, Arntl/Bmal1 and Clock, which fit the known feedback loop transcriptional regulation of these genes in the pathway." (PMID 41360887, 2025). "Indeed, we have previously demonstrated that per2 knock-out animals develop diabetes-like retinopathy." (PMID 24736612, 2014). "Our study suggests that Per2 gene could play a role in regulation of glucose homeostasis in diabetes particularly through the regulation of hepatic glycogen contents." (PMID 22934083, 2012). "Thus, ARNTL rs12363415 was connected with type 2 diabetes mellitus in women, while CRY2 rs2292912 and PER2 rs934945 were connected with dyslipidemia in men." (PMID 34066863, 2021). "A list of 15 known clock genes from the primary (Arntl, Clock, Npas2, Per1, Per2, Per3, Cry1, Cry2), secondary (Nrd1d1, Nr1d2, Rora, Rorb, Rorc), and accessory TTFL loops (Nfil3, Dbp) were selected to investigate the effect of diabetes on their rhythmic expression." (PMID 38039846, 2024). "The mRNA expression of BMAL1, PER1, PER2, and PER3 in leukocytes was observed to be lower in non-diabetic individuals, as compared to those with diabetes." (PMID 37475884, 2023).